UBE4B (ubiquitination factor E4B)
Description:
Ubiquitin-protein ligase that probably functions as an E3 ligase in conjunction with specific E1 and E2 ligases (By similarity). May also function as an E4 ligase mediating the assembly of polyubiquitin chains on substrates ubiquitinated by another E3 ubiquitin ligase (By similarity). May regulate myosin assembly in striated muscles together with STUB1 and VCP/p97 by targeting myosin chaperone UNC45B for proteasomal degradation.
Synonyms: HDNB1; KIAA0684; UFD2; UBOX3; E4; UFD2A
Tractability: PROTAC: ubiquitination databases record sites on it; its protein half-life has been measured.
Gene: Protein-coding gene on chromosome 1 (10,032,832 to 10,181,244, forward strand). Ensembl gene ENSG00000130939.
Subcellular location: Cytoplasm; Nucleus
Gene Ontology:
Molecular function: protein binding; ubiquitin protein ligase activity; ubiquitin-ubiquitin ligase activity; enzyme binding; ATP binding; ubiquitin-protein transferase activity
Biological process: granzyme-mediated apoptotic signaling pathway; proteasome-mediated ubiquitin-dependent protein catabolic process; response to UV; ubiquitin-dependent protein catabolic process; ERAD pathway; protein polyubiquitination; protein ubiquitination
Cellular component: cytoplasm; nucleus; ubiquitin ligase complex
Genetic constraint (gnomAD): Loss-of-function variants: 24 observed, 142.29 expected, observed/expected ratio (o/e) 0.17, 90% interval 0.12 to 0.24. The upper end of that interval is the gene's LOEUF score, 0.24, which puts it in group 1 of 6, group 1 being the genes least tolerant of losing a copy. Missense variants: 1,160 observed, 1,712.5 expected, observed/expected ratio (o/e) 0.68, 90% interval 0.64 to 0.71. Synonymous variants: 591 observed, 642.39 expected, observed/expected ratio (o/e) 0.92, 90% interval 0.86 to 0.99.
Homologues: Orthologues: dog UBE4B (97% identical), rabbit UBE4B (96% identical), pig UBE4B (95% identical), rat Ube4b (95% identical), guinea pig UBE4B (94% identical), chimpanzee UBE4B (94% identical), mouse Ube4b (88% identical), tropical clawed frog ube4b (81% identical), zebrafish ube4b (74% identical), Drosophila melanogaster Ube4B (34% identical), Caenorhabditis elegans ufd-2 (23% identical). Paralogues in human: UBE4A (20% identical).
Diseases named in the same sentence as UBE4B in open-access papers:
UBE4B is named in the same sentence as 45 diseases in open-access papers, as found by Europe PMC text mining. Sharing a sentence is not in itself a finding about the gene and the disease. The quoted sentences say what the papers report.
neuroblastoma (8 papers, 2014 to 2025). Neuroblastoma (NB) is the most common solid, extracranial childhood tumor. "Deletions in chromosome 1p36 have been detected in approximately one-third of neuroblastoma tumors and are associated with high-risk tumor features and a poor prognosis, suggesting a potential role for UBE4B as a tumor suppressor gene." (PMID 37957138, 2023). "UBE4B gene expression is strongly associated with neuroblastoma patient outcomes, and UBE4B ubiquitin ligase activity on the endosomal membrane surface is required for appropriate EGFR trafficking and lysosomal degradation in neuroblastoma cells." (PMID 37957138, 2023). "The combined associations of UBE4B expression and UBE4B-mediated intracellular signaling pathway activity with patient outcomes suggests that these pathways play critical roles in neuroblastoma pathogenesis and represent potential therapeutic targets." (PMID 37957138, 2023). "In mammalian neuroblastoma cells, overexpression of UBE4B and STUB1, which encodes the E3 ligase CHIP, increases the ubiquitination and degradation of Tau." (PMID 34078905, 2021). "The functional role of UBE4B in neuroblastoma pathogenesis and its association with other prognostic factors, however, are poorly understood." (PMID 27014418, 2016). "Low UBE4B gene expression is associated with poor outcomes in patients with neuroblastoma and with worse outcomes in all patient subgroups." (PMID 27014418, 2016). "We have identified an association between UBE4B protein expression and poor prognostic features for children with neuroblastoma, although we were unable to demonstrate a significant association between UBE4B protein expression and patient outcomes." (PMID 27014418, 2016). "We have demonstrated associations between UBE4B gene expression and neuroblastoma patient outcomes and prognostic features." (PMID 27014418, 2016). "We evaluated the association of UBE4B gene expression with neuroblastoma patient outcomes using the R2 Platform." (PMID 27014418, 2016). "To evaluate the potential association of UBE4B gene expression with known clinical and biological factors associated with neuroblastoma patient outcomes, we analyzed results from microarray analyses of neuroblastoma tumors." (PMID 27014418, 2016). "UBE4B protein expression was associated with neuroblastoma tumor differentiation, and decreased UBE4B protein levels were associated with high-risk features." (PMID 27014418, 2016). "In neuroblastoma patient cohorts separated by treatment risk group, low UBE4B expression was associated with lower event-free and overall survival rates in patients with both low and intermediate risk neuroblastoma and in those with high-risk neuroblastoma." (PMID 27014418, 2016). "We analyzed the associations of UBE4B gene and protein expression with neuroblastoma patient outcomes and with tumor prognostic features and histology." (PMID 27014418, 2016). "We have identified an association between UBE4B gene expression and neuroblastoma patient outcomes, suggesting a potential role for UBE4B as a tumor suppressor gene." (PMID 27014418, 2016). "We evaluated the association of UBE4B gene expression with neuroblastoma patient outcomes, using results from microarray analyses of neuroblastoma tumors obtained from the R2 Genomics Analysis and Visualization Platform." (PMID 27014418, 2016). "To explore the potential roles of Ku70 and c-FLIPL as mediators of the established association between UBE4B expression and neuroblastoma patient outcomes, we hypothesized that Ku70 and c-FLIPL could be targets of UBE4B ubiquitin ligase activity." (PMID 37957138, 2023). "We hypothesized that UBE4B gene and protein expression would be associated with neuroblastoma patient outcomes and other prognostic features and with neuroblastoma tumorigenesis." (PMID 27014418, 2016).
neuroblastoma (continued). "In neuroblastoma patient cohorts separated by tumor stage, low UBE4B gene expression was again associated with lower relapse-free, event-free, and overall survival rates in patients with both low stage and high stage disease and with stage 4 disease separately." (PMID 27014418, 2016). "This link between a known cytogenetic risk factor, GFR trafficking, and neuroblastoma tumor histology suggests UBE4B-mediated GFR trafficking may contribute to the poor prognosis of neuroblastoma tumors with 1p36 deletions." (PMID 27014418, 2016). "The significant association of low UBE4B expression with lower survival rates in cohorts of low stage and younger patients suggests UBE4B may be a novel predictor of relapse in children with low and intermediate risk neuroblastoma." (PMID 27014418, 2016). "Further studies are also needed to confirm whether UBE4B protein function is also linked to patient prognosis and whether UBE4B plays a functional role in neuroblastoma tumor differentiation." (PMID 27014418, 2016). "These links between UBE4B ubiquitin ligase activity and GFR trafficking and additional signaling pathways therefore suggest potential alternative mechanisms that could also mediate the observed associations between UBE4B gene expression and neuroblastoma patient outcomes." (PMID 37957138, 2023). "In contrast, findings have shown the aberrant downregulation of UBE4B gene expression in neuroblastoma and oral squamous cell carcinoma." (PMID 40701960, 2025). "Instead, abnormal downregulation of UBE4B gene expression has been observed in neuroblastoma and oral squamous cell carcinoma." (PMID 40701960, 2025). "Neuroblastoma cell lines with depleted UBE4B were analyzed by Western blot for Ku70 and c-FLIPL protein levels, and increased Ku70 and c-FLIPL protein levels were seen in all cell lines with depleted UBE4B." (PMID 37957138, 2023). "Decreased expression of UBE4B is correlated with low cellular differentiation in neuroblastoma tumors." (PMID 37754259, 2023). "In mammalian neuroblastoma cells, UBE4B-mediated Tau clearance was accelerated by co-expression of STUB1, which encodes an ubiquitin E3 ligase for Tau." (PMID 34078905, 2021). "To investigate the mechanism by which UBE4B degraded Tau, we first determined if UBE4B affected Tau ubiquitination in SH-SY5Y neuroblastoma cells." (PMID 34078905, 2021). "In mammalian neuroblastoma cells and a mouse tau overexpression model, UBE4B, and STUB1 E3 ligases ubiquitinated Tau proteins and induced autophagy-mediated Tau degradation." (PMID 34078905, 2021). "The UBE4B gene is located within the chromosome 1p36 region frequently deleted in neuroblastoma tumors, and therefore UBE4B represents a candidate tumor suppressor gene within this region." (PMID 27014418, 2016). "To evaluate changes in UBE4B gene expression during neuroblastoma tumor cell differentiation, we performed RNA-sequencing on neuroblastoma tumor cells before and after 13-cis-retinoic acid (CRA) treatment." (PMID 27014418, 2016). "UBE4B therefore represents a novel molecular marker of neuroblastoma tumor differentiation and intratumoral heterogeneity and also represents a potential target for novel drug development." (PMID 27014418, 2016). "Although we have demonstrated associations between UBE4B gene and protein expression and a number of critical neuroblastoma prognostic variables, studies are ongoing to determine whether UBE4B expression is independently associated with neuroblastoma patient outcomes." (PMID 27014418, 2016). "We then evaluated UBE4B expression for associations with prognostic factors and with levels of phosphorylated ERK in neuroblastoma tumors and cell lines." (PMID 27014418, 2016). "We have shown that neuroblastoma tumors with 1p36 deletion have lower UBE4B expression levels, suggesting that decreased UBE4B gene expression is a potential contributor to the poor prognosis of neuroblastoma patients with 1p36 deletions." (PMID 27014418, 2016).
neuroblastoma (continued). "For these infants with metastatic disease, UBE4B protein expression may serve as a novel molecular marker to distinguish stage 4 from 4S disease, and UBE4B expression and function may underlie the dramatic clinical and biologic differences between these two subtypes of neuroblastoma." (PMID 27014418, 2016). "UBE4B levels reportedly influenced neuroblastoma tumor cell proliferation, and UBE4B was overexpressed in various brain tumors." (PMID 24587254, 2014). "Expression of the UBE4B ubiquitin ligase is strongly associated with neuroblastoma patient outcomes, but the functional roles of UBE4B in neuroblastoma pathogenesis are not known." (PMID 37957138, 2023). "In neuroblastoma cells, UBE4B participates in lysosomal degradation of EGFR." (PMID 36440598, 2022). "We have confirmed an association between UBE4B expression and neuroblastoma patient outcomes and prognostic features and demonstrated that reduced UBE4B expression in neuroblastoma tumors was associated with a lack of differentiation." (PMID 27014418, 2016). "Furthermore, the association of low UBE4B expression with worse patient outcomes in all patient subsets suggests that alternate mechanisms regulating UBE4B gene expression other than 1p36 deletion are likely involved in neuroblastoma tumors." (PMID 27014418, 2016). "Reduced UBE4B protein expression in neuroblastoma tumors was associated with high-risk features, a lack of differentiation, and with ERK activation." (PMID 27014418, 2016). "We screened neuroblastoma tumor samples for UBE4B protein expression using immunohistochemistry." (PMID 27014418, 2016). "To determine whether UBE4B protein expression was also associated with neuroblastoma patient outcomes and prognostic features, we analyzed neuroblastoma tumor samples for UBE4B expression by immunohistochemistry." (PMID 27014418, 2016). "Increased understanding of UBE4B targets and downstream signaling pathways will help identify the functional links between UBE4B expression and patient outcomes and identify novel targets for the development of new treatment combinations for children with neuroblastoma." (PMID 37957138, 2023). "Similarly, ITCH mediates ubiquitination of the Hrs protein, suggesting further interactions between UBE4B and ITCH may occur on the endosomal membrane surface and contribute to the associations of UBE4B expression with neuroblastoma patient outcomes." (PMID 37957138, 2023). "In order to evaluate whether UBE4B protein expression was correlated with any other known neuroblastoma prognostic factors, UBE4B staining intensity was compared in patient cohorts divided by tumor stage, treatment risk group, MYCN amplification, Shimada histology, and patient age at diagnosis." (PMID 27014418, 2016). "Our results have identified novel interactions and novel targets for UBE4B ubiquitin ligase activity and a direct role of the ITCH-UBE4B E3-E4 ubiquitin ligase complex in neuroblastoma cell responses to HDAC inhibition." (PMID 37957138, 2023). "To determine the primary pathway of UBE4B and STUB1-mediated Tau degradation, we co-overexpressed UBE4B and STUB1 with Tau in neuroblastoma cells, and treated the cells with either the UPS inhibitor MG132 or the ALS inhibitors." (PMID 34078905, 2021). "Recruitment of UBE4B to endosomal membranes is dependent on binding with Hrs, and we demonstrated that UBE4B ubiquitin ligase activity is required for appropriate EGFR trafficking and lysosomal degradation in neuroblastoma cells." (PMID 37957138, 2023). "In addition, pepstatin A (PEPA) alone and E64D plus PEPA (E64D + PEPA), autophagy inhibitors, significantly inhibited Tau degradation, suggesting that ALS was the major pathway of UBE4B and STUB1-mediated Tau degradation in neuroblastoma cells." (PMID 34078905, 2021). "Since the knockdown of STUB1 in neuroblastoma cell lines showed no change in Tau levels in the presence of UBE4B, we further examined the importance of STUB1 in the in vivo Drosophila model system." (PMID 34078905, 2021).
neuroblastoma (continued). "In order to determine whether UBE4B expression was also associated with RAS/MAPK pathway signaling activity in neuroblastoma tumor cells, we determined levels of UBE4B and total and phosphorylated MEK and ERK expression in established neuroblastoma cell lines and patient tumor samples." (PMID 27014418, 2016).
breast carcinoma (6 papers, 2014 to 2025). "Overall survival rates were significantly lower in human liver cancer and breast cancer with UBE4B and Wip1 overexpression." (PMID 40175346, 2025). "UBE4B will ultimately provide the most effective way to take advantage of the ever-increasing list of new biological therapies for breast cancer." (PMID 24587254, 2014). "In this paper, we first reported UBE4B protein expression in breast cancer tissues and we determined that breast cancer tissues have significantly higher levels of UBE4B than normal tissues." (PMID 24587254, 2014). "We detected UBE4B protein expression in normal breast tissues and breast cancer tissues." (PMID 24587254, 2014). "UBE4B expression was higher in breast cancer tissues than in normal breast tissues." (PMID 24587254, 2014). "Kaplan–Meier survival curves revealed that patients with breast cancer and liver cancers with a high level of Wip1 (PPMID) and UBE4B had a significantly lower overall survival time (kmplot.com)." (PMID 40175346, 2025). "Indeed, the evaluation of an ER+ breast cancer cohort with a 10‐year follow‐up (Table EV6), identified increased AHR, DDA1, and UBE4B levels in the primary tumors that relapsed (EV4O and Q, Table EV7)." (PMID 35174975, 2022).
hepatocellular carcinoma (5 papers, 2015 to 2025). A malignant tumor that arises from hepatocytes. "In hepatocellular carcinoma, the upregulation of UBE4B expression is associated with a poor prognosis and tumour immune infiltration." (PMID 40701960, 2025). "UBE4B was also found upregulated in human primary hepatocellular carcinoma tissues and this amplified expression is correlated with poor outcome." (PMID 33670160, 2021). "It was further observed that the gene locus of UBE4B (1p36.22) is a susceptible candidate locus for hepatitis B virus (HBV) related hepatocellular carcinoma (HCC), forming a possible link between UBE4B/UFD2 and cancer development and tumor suppression." (PMID 25806049, 2015).